DSPP (dentin sialophosphoprotein)
Description:
DSP may be an important factor in dentinogenesis. DPP may bind high amount of calcium and facilitate initial mineralization of dentin matrix collagen as well as regulate the size and shape of the crystals.
Synonyms: DPP; DSP; DMP3; DFNA39; DGI1
Tractability: Antibody: its Gene Ontology location is reachable by antibodies, with high confidence; UniProt places it where antibodies can reach, with medium confidence; UniProt predicts a signal peptide or a membrane-spanning region.
Gene: Protein-coding gene on chromosome 4 (87,608,529 to 87,616,873, forward strand). Ensembl gene ENSG00000152591.
Subcellular location: Secreted, extracellular space, extracellular matrix
Pathways (Reactome):
Extracellular matrix organization: ECM proteoglycans
Gene Ontology:
Molecular function: calcium ion binding; collagen binding; extracellular matrix structural constituent
Biological process: dentinogenesis; odontoblast differentiation; regulation of odontoblast differentiation
Cellular component: cytoplasm; extracellular matrix; extracellular region; non-collagenous component of interstitial matrix; nucleus
Genetic constraint (gnomAD): Loss-of-function variants: 28 observed, 30.21 expected, observed/expected ratio (o/e) 0.93, 90% interval 0.69 to 1.27. The upper end of that interval is the gene's LOEUF score, 1.27, which puts it in group 5 of 6, group 1 being the genes least tolerant of losing a copy. Missense variants: 1,266 observed, 1,620.6 expected, observed/expected ratio (o/e) 0.78, 90% interval 0.75 to 0.82. Synonymous variants: 473 observed, 467.81 expected, observed/expected ratio (o/e) 1.01, 90% interval 0.94 to 1.09.
Gene-disease validity (ClinGen):
ClinGen rates the evidence that DSPP causes each of these diseases.
dentinogenesis imperfecta (autosomal dominant): Definitive. Dentinogenesis imperfecta (DGI) is a hereditary dentin defect characterized by abnormal dentin structure resulting in abnormal tooth development.
Homologues: Orthologues: chimpanzee DSPP (86% identical), dog DSPP (54% identical), mouse Dspp (42% identical), rat Dspp (42% identical).
Diseases named in the same sentence as DSPP in open-access papers:
DSPP is named in the same sentence as 55 diseases in open-access papers, as found by Europe PMC text mining. Sharing a sentence is not in itself a finding about the gene and the disease. The quoted sentences say what the papers report.
dentinogenesis imperfecta (23 papers, 2007 to 2025). "A patient presenting with dentinogenesis imperfecta (Family 21) is heterozygous for a DSPP frameshift variant." (PMID 37361548, 2023). "A patient presenting with dentinogenesis imperfecta was found to be heterozygous for a likely pathogenic DSPP frameshift variant (NM_014208.3: c.1439_1454del; p.Glu480AlafsTer829)." (PMID 37361548, 2023). "Dentin sialophosphoprotein (DSPP), a marker of late odontoblast differentiation, is crucial for the mineralization of tooth dentin and has been implicated in dentinogenesis imperfecta." (PMID 35273362, 2022). "A large number of previous studies demonstrated that DSPP is a dentinal-specific protein, andDSPPgene mutations lead to dentin dysplasia and dentinogenesis imperfecta." (PMID 34430959, 2021). "Mutations in the gene encoding dentin sialophosphoprotein (DSPP) have been identified to cause dentinogenesis imperfecta (DGI) Types II and III and dentin dysplasia (DD) Type II." (PMID 34201399, 2021). "Nonsyndromic dentin defects classified as type II dentin dysplasia and types II and III dentinogenesis imperfecta are caused by mutations in DSPP (dentin sialophosphoprotein)." (PMID 26788535, 2016). "Mutations in the dentin sialophosphoprotein (DSPP) gene cause dentinogenesis imperfecta." (PMID 29672573, 2018). "Mutations in the DSPP gene in humans cause a non-syndromic inheritable dominant dental disorder, known as dentinogenesis imperfecta (DGI)." (PMID 41438216, 2025). "Therefore, further studies are still needed to completely understand the molecular pathogenesis of dentinogenesis imperfecta associated with DSPP mutations in order to develop an effective and preventative therapeutic strategy for clinical management of DGI patients in the future." (PMID 41438216, 2025). "All four of the families with DSPP 5′ (N-terminal) mutations exhibited dental phenotype consistent with a diagnosis of dentinogenesis imperfecta type III (DGI-III)." (PMID 35627243, 2022). "Dentine dysplasia type II and the two non-syndromic subtypes of dentinogenesis imperfecta, type II and III, are caused by variable types of mutations at different locations of the DSPP gene, which implies possible allelic nature of those disorders." (PMID 39559541, 2024). "DSPP variants have been shown to cause Type II and Type III dentinogenesis imperfecta and dentin dysplasia II, with other candidate genes possibly causing those conditions as well." (PMID 37361548, 2023). "In this study, we examined the roles of IRE1α in odontoblast development and dentin formation in wild-type mice as well as in DsppP19L mutant mice, which express a pathogenic variant of dentin sialophosphoprotein (P19L-DSPP) and exhibit a dentinogenesis imperfecta (DGI)-like phenotype." (PMID 41438216, 2025). "DSPP and DMP1 gene mutations in humans and mice caused dentinogenesis imperfecta (DGI) 5–9." (PMID 37790473, 2023). "We previously generated a knockin mouse model expressing a mouse equivalent (DSPP, p.P19L) of human mutant DSPP (p.P17L; referred to as “DsppP19L/+”), and reported that DsppP19L/+ and DsppP19L/P19L mice manifested a dentin phenotype resembling human dentinogenesis imperfecta (DGI)." (PMID 34630144, 2021). "For the opposite case, u(MA, HA), the gene DSPP, related to deafness and tooth abnormalities (dentin dysplasia and dentinogenesis imperfecta) were found alongside PLAG1, DCLRE1C and PLCB2 to be associated with adenomas, severe immunodeficiency and platelet deficiency respectively." (PMID 29161290, 2017). "BMP2-deficient teeth display morphological features similar to dentinogenesis imperfecta (DGI), which is associated with mutations in the DMP1 and DSPP genes." (PMID 40133254, 2025). "Teeth lacking Bmp2 exhibit a morphology reminiscent of dentinogenesis imperfecta (DGI), associated with mutations in dentin matrix protein 1 (DMP1) and dentin sialophosphoprotein (DSPP) genes." (PMID 37790473, 2023).
dentinogenesis imperfecta (continued). "More importantly, as the major dentinal non-collagenous proteins, DSPP is essential for dentin mineralization, while DMP-1 is also specific for dentin and is considered as a candidate gene for dentinogenesis imperfecta." (PMID 23675415, 2013). "Non-syndromic dentin defects categorized as dentin dysplasia type II (DD-II), dentinogenesis imperfecta type II (DGI-II) and type III (DGI-III) are generally caused by dominant mutations in dentin sialophosphoprotein (DSPP), which encodes the most abundant non-collagenous matrix component of dentin." (PMID 23227268, 2012).
dentin dysplasia type II (14 papers, 2007 to 2025). Dentin dysplasia type II (DD-II) is a rare mild form of dentin dysplasia (DD) characterized by normal tooth roots but abnormal primary dentition. "Mutations in Dentin Sialophosphoprotein (DSPP) are known to cause, in order of increasing severity, dentin dysplasia type-II (DD-II), dentinogenesis imperfecta type-II (DGI-II), and dentinogenesis imperfecta type-III (DGI-III)." (PMID 35627243, 2022). "DSPP defects cause an overlapping spectrum of phenotypes classified as dentin dysplasia type II and dentinogenesis imperfecta types II and III." (PMID 34667213, 2021). "DSPP has been linked with dentin biomineralization, specifically, dentinogenesis imperfecta types II and III and dentin dysplasia type II, arising due to genetic deficiency in DSPP." (PMID 34401209, 2021). "DI types II, III, and dentin dysplasia type II are caused because of mutations in the dentin sialophosphoprotein (DSPP) gene." (PMID 29403236, 2017). "Mutations in DSPP cause inherited dentin defects categorized as dentin dysplasia type II and dentinogenesis imperfecta type II and type III." (PMID 21291557, 2011). "Dentin sialophosphoprotein (Dspp) is critical for proper dentin biomineralization because genetic defects in DSPP cause dentin dysplasia type II and dentinogenesis imperfecta types II and III." (PMID 20687161, 2011). "Mutation p.Y6D was found to be associated with type II dentin dysplasia (DD), this mutation is located in the signal peptide domain of DSPP, and disabled the entry of DSPP into the endoplasmic reticulum." (PMID 17686168, 2007). "Heterogeneous mutations in human DSPP have been identified to be associated with hereditary dentin disorders including dentinogenesis imperfecta type II (DGI-II), DGI-III, and dentin dysplasia type II (DD-II)." (PMID 39922489, 2025). "DSPP mutations in humans are associated with dentinogenesis imperfecta type II (DGI-II, OMIM 125490) and DGI-III (OMIM 125500), as well as dentin dysplasia type II (DD-II, OMIM 125420) and DD-I (MIM 125400)." (PMID 35883659, 2022).
dentin dysplasia (12 papers, 2007 to 2024). Dentin dysplasia (DD) is a rare disorder belonging to the group of hereditary dentin defects and is characterized by abnormal dentin structure and root development resulting in abnormal tooth development. "So far, around 50 different DSPP variants have been described in patients with DI or dentin dysplasia from various ethnic groups." (PMID 38630328, 2024). "Several inherited disorders affect dentinogenesis, including dentinogenesis imperfecta/dentin dysplasia, caused by mutations in dentin sialophosphoprotein (DSPP)." (PMID 33778330, 2021). "In fact, DSPP (Dentin Sialophosphoprotein) p.Tyr6Asp in the signal peptide region abolishes the signal peptide function, and prevents DSPP protein from entering endoplasmic reticulum, resulting in dentin dysplasia." (PMID 36207673, 2022). "Mutations in the dentin sialophosphoprotein gene (DSPP) on chromosome 4q21 have been linked to DI and another dentinal abnormality known as dentin dysplasia (DD)." (PMID 34976063, 2021). "In exon 5 at the 3′ end of DSPP, deletions causing frame shift mutations were responsible for DGI and dentin dysplasia (DD)." (PMID 26973538, 2016).
dentinogenesis imperfecta type 3 (6 papers, 2011 to 2025). "It is known that dentinogenesis imperfecta type II and dentinogenesis imperfecta type III are associated with a gene mutation of the dentin sialophosphoprotein (DSPP), which is highly expressed in odontoblasts and is located on chromosome 4q21.3." (PMID 40881539, 2025). "In contrast so-called shell teeth affected by dentinogenesis imperfecta type III (OMIM#125500) which is also caused by genetic defects of DSPP, exhibit excessively large pulp cavities." (PMID 26578979, 2015). "Since the features associated with the Dlx3 deletion were shown to be due to down-regulation of dentin sialophosphoprotein (Dspp), they appear to rather phenocopy the so-called shell teeth observed in dentinogenesis imperfecta type III (OMIM#125500) which is caused by mutations in the DSPP gene." (PMID 26578979, 2015). "It is a cleaved product of dentin sialophosphoprotein (DSPP), and the absence of DSPP has been associated with dentinogenesis imperfecta type III." (PMID 36359301, 2022).
oral cancers (5 papers, 2010 to 2022). "DSPP gene has been previously linked to oral cancers, but MMP20-DSPP co-localization and interaction has been observed in breast, colorectal and other cancers as well." (PMID 36425062, 2022). "Published reports of the mechanistic network and interplay between these proteins provide a framework for studying their hierarchical interactions with DSPP/MMP20 in oral cancer progression, particularly invasion and metastasis." (PMID 32630820, 2020). "Published reports show that MMP2 and MMP9 are upregulated in OSCCs, where they aid in the invasiveness of oral cancer cells, and silencing DSPP decreases oral cancer cell invasion." (PMID 32630820, 2020). "Further studies show that MMP20/DSPP silencing in OSCC cells resulted in the downregulation of oral cancer stem cell markers and increased sensitivity of OSCC cells to cisplatin treatment." (PMID 32630820, 2020). "More significantly, this is the first report on a study that investigated the effects of DSPP-silencing on the tumorigenic profiles of an oral cancer cell line." (PMID 21103065, 2010). "DSPP-silencing in OSC2 cell decreased salient hallmarks of oral tumorigenesis and provides the first functional evidence of a potential key role for DSPP in oral cancer biology." (PMID 21103065, 2010). "While a detailed study of the mechanism of DSPP-oral cancer tumorigenesis was beyond the scope of our present report, our current data provides a framework for on-going study focused on deciphering DSPP mechanistic network involved in oral cancer biology." (PMID 21103065, 2010). "Reviews of the specific genes products profiled in this study, following DSPP silencing, indicate that none of them have, until now, been associated with the potential role of DSPP in oral cancer." (PMID 21103065, 2010). "Collectively, these results suggest a regulatory role for DSPP in the upregulation and activation of the SIBLING-partnering MMPs as well as angiogenesis in oral cancer." (PMID 21103065, 2010). "Because BSP, DSPP, and OPN were upregulated in OSCCs, while DMP1 and MEPE were absent, we designated BSP, DSPP, and OPN as oral cancer-associated SIBLNGs." (PMID 22410369, 2012). "However, there currently are no data on the functional and mechanistic role of DSPP in oral cancer development and progression." (PMID 21103065, 2010).
oral squamous cell carcinoma (5 papers, 2010 to 2023). "Another member of the SIBLING family, dentin sialophosphoprotein (DSPP; isolated from dentine ECM and with low levels in bones), has been shown to be upregulated in human oral squamous cell carcinoma." (PMID 36765749, 2023). "Recent reports highlight the potential tumorigenic role of Dentin Sialophosphoprotein (DSPP) and its cognate partner Matrix Metalloproteinase 20 (MMP-20) in Oral Squamous Cell Carcinomas (OSCCs)." (PMID 32630820, 2020). "We recently reported the up-regulation of BSP, DSPP, and OPN, in human oral squamous cell carcinomas (OSCCs) and in some human oral epithelial dysplasia (OEDs)." (PMID 21103065, 2010).
osteogenesis imperfecta (5 papers, 2012 to 2026). Osteogenesis imperfecta (OI) comprises a heterogeneous group of genetic disorders characterized by increased bone fragility, low bone mass, and susceptibility to bone fractures with variable severity. "These subtypes can either appear in association with osteogenesis imperfecta (DI–I) or as an isolated finding associated with mutations in the dentin sialophosphoprotein gene DSPP (DI–II and DI–III)." (PMID 29512331, 2018). "This initial screening allowed us to identify families with osteogenesis imperfecta (caused by COL1A1 and COL1A2 mutations), as well as mutations in the non-repetitive regions of DSPP." (PMID 35627243, 2022).
deafness (4 papers, 2014 to 2023). An inherited or acquired condition characterized by the complete loss of the ability to hear from one or both ears. "In addition, Dentin Sialophosphoprotein (DSPP), another member of the SIBLING proteins (DSPP and DMP1 share many similarities in both their gene and protein structures), is from a known deafness gene (DFNA39) that can cause congenital sensorineural deafness." (PMID 37106825, 2023). "We identified many well-established deafness mutations (e.g., GJB2 c.235delC, GJB2 p.V37I, SLC26A4 c.919-2A > G, as well as previously un-reported novel mutations (e.g., DSPP c.3264_3265insCGATAGCGG, p.S1088delinsSRX) which we predict to be deleterious to protein functioning." (PMID 25342930, 2014).
prostate carcinoma (3 papers, 2010 to 2016). A carcinoma that arises from epithelial cells of the prostate gland. "Expression of SIBLINGS, notably BSP and OPN is associated with prostate cancer progression; OPN and BSP can be used as biomarkers of bone metastasis and DSPP has been proposed as a biomarker for prostate cancer diagnosis." (PMID 24213501, 2012). "Western blot analysis showed significantly elevated BSP and DSPP in prostate cancer-derived cells." (PMID 27331624, 2016). "Given, particularly, the consistent upregulation of BSP and DSPP in prostate cancer, it is plausible to suggest that BSP and DSPP levels may predict progression of benign prostatic neoplasms to malignant disease." (PMID 27331624, 2016). "Recent studies also have shown significant levels of expression of DSPP (and other members of the SIBLING family) in metabolically active ductal epithelial cells, and its upregulation in a subset of breast, oral, lung, and prostate cancers." (PMID 21103065, 2010).
hearing loss (2 papers, 2020 to 2021). "Additional hearing loss families, all of East Asian ethnicity, have been identified to have splice or missense variants within the first five exons of DSPP." (PMID 33924653, 2021). "DSPP: Variants in DSPP (MIM 125485; 4q22.1) were first identified as a cause of AD hearing loss DFNA39 with dentinogenesis (MIM 605594) in Chinese families with dentinogenesis imperfecta 1 and adult-onset progressive sensorineural high-frequency hearing loss." (PMID 33924653, 2021).
Alzheimer disease (1 paper, 2021). A progressive, neurodegenerative disease characterized by loss of function and death of nerve cells in several areas of the brain leading to loss of cognitive function such as memory and language. "Eleven of those follow an autosomal-dominant inheritance pattern and span a wide range of phenotypes, including three genes linked to various dental issues (AMTN, ENAM, DSPP) and APP known to cause Alzheimer disease when duplicated." (PMID 33315133, 2021).
cervical neoplasms (1 paper, 2019). "This study aimed to survey the expression of MMP20 and its cognate DSPP partner in the breast, colon, prostate, thyroid, and cervical neoplasms." (PMID 30932369, 2019). "Significantly high expression levels of MMP20 and DSPP were observed in the malignant breast, colon, prostate, thyroid, and cervical neoplasms compared with their benign and normal counterparts." (PMID 30932369, 2019). "Accordingly, the potential biologic significance of DSPP and MMP20 levels in the breast, colon, and cervical neoplasms is still unclear." (PMID 30932369, 2019).
fibrosis (1 paper, 2019). the formation of excess fibrous connective tissue in an organ or tissue in a reparative or reactive process. "Alternatively, THBS2 was chosen for its novelty in kidney fibrosis, while BSP and DSPP were selected to validate novel MCPs in fibrosis." (PMID 31723159, 2019).
follicular adenoma (1 paper, 2019). "However, expression levels in normal prostate and thyroid were relatively lower than in their neoplastic counterpart except for metastatic prostatic adenocarcinoma and follicular adenoma of the thyroid, where DSPP levels compared with their normal counterpart." (PMID 30932369, 2019).
hypophosphatemia (1 paper, 2016). Lower than normal levels of phosphates in the circulating blood. "Ablation of the Fam20c gene in conditional knockout mice affects tooth and bone development by downregulation of SIBLING family of proteins such as DMP1 and DSPP and by increasing FGF23 in serum and promoting phosphate excretion and hypophosphatemia." (PMID 27187611, 2016).